NLRP3 (NLR family pyrin domain containing 3)
Diseases named in the same sentence as NLRP3 in open-access papers (continued):
Sharing a sentence is not in itself a finding about the gene and the disease.
cancer (continued). "Numerous in vitro studies suggested the dynamic role of NLRP3 inflammasome as a signaling platform for inflammatory responses elaboration which contributes to cancer progression by providing a favorable environment." (PMID 39433537, 2024). "Cryptotanshinone treatment was able to inhibit cancer cell progression, probably through inhibiting NLRP3." (PMID 39144184, 2024). "Lastly, the third phase, from 2020 to 2023, concentrates on ‘homeostasis, cellular, binding, NLRP3 inflammasome, cancer therapy, ablation,’ indicating a sustained focus on mechanism and pathway studies." (PMID 38962561, 2024). "Based on the role of the inflammasome in the pathogenesis of cancer, therapeutic approaches aimed to inhibit the NLRP3-induced proinflammatory cytokines were tested." (PMID 38543085, 2024). "Contrary to acute conditions, the efficacy of NLRP3 inhibition for the treatment of chronic diseases, such as metabolic, cardiovascular, cancer, and neurodegenerative disorders, will require treatment for long dosing duration." (PMID 39188718, 2024). "The NLRP3 inflammatory vesicle plays a key role in different types of cancers and is the most comprehensively studied inflammatory vesicle involved in the development of cancer." (PMID 38731276, 2024). "In various preclinical and clinical studies, the role of NLRP3 has been extensively explored and a correlation between lower expression of NLRP3 and advanced cancer has been established." (PMID 39318624, 2024). "Correlation analysis also showed a positive correlation between the NLRP3 gene expression leve and the M1 macrophage infiltration level in various cancer types, based on analyses of TCGA data." (PMID 38062129, 2024). "Considering the reported role of NLRP3 in chronic conditions such as cancer, cardio-metabolic and neurodegenerative diseases, we believe this is particularly relevant considering the requirement of long-term treatment." (PMID 39188718, 2024). "A pathological role for NLRP3/IL-1β has been demonstrated in several cancer models by promoting immunosuppression, tumor progression and reduced survival." (PMID 39188718, 2024). "A recent study showed significant alterations in the expression of NLRP3 inflammasome component genes in 15 of the 24 cancer types." (PMID 38804602, 2024). "Here, NLRP3 is activated through endogenous signals in a tissue specific manner in rheumatological, metabolic, neurodegenerative, cardiovascular diseases and cancer." (PMID 39188718, 2024). "Autophagic cell death in cancer cells can stimulate ATP signaling through purinergic receptors, either autocrine or paracrine, leading to activation of the NLRP3 inflammasome and the production of IL1β." (PMID 38892354, 2024). "If the NLRP3 inflammasome is to be exploited as a therapeutic target, further laboratory-based investigation is required to determine its role in cancer." (PMID 39516433, 2024). "For example, NLR family pyrin domain containing 3 (NLRP3) activation induced the M2-like macrophage polarization of TAMs in a murine model of PDAC to promote cancer cell lung metastasis." (PMID 38672552, 2024). "The NLRP3 inflammasome is of particular interest, due to its ability to have both protective and damaging effects on carcinogenesis, depending on the type of cancer." (PMID 39769450, 2024). "In diseases, such as gout, atherosclerosis, type II diabetes, cancers, and others, a pathological NLRP3 inflammasome activation was involved." (PMID 39199260, 2024). "We also showed that Alu RNA is stored and transported by exosomes and that CRC-derived exosomal Alu RNA can be transferred to cancer cells, in which it promotes cancer progression by inducing EMT via NLRP3 inflammasome activation." (PMID 38486106, 2024). "This narrative review article discusses only the role and therapeutic significance of the NLRP3 inflammasome in various cancers." (PMID 39769450, 2024).
cancer (continued). "At present, it has been reported that NLRP3 inflammasome positively regulates apoptosis of cancer cells, which is inconsistent with the conclusion that inhibition of NLRP3 inflammasome induces apoptosis of HCC cells in above studies." (PMID 37153780, 2023). "While some studies proposed a preventive role for the NLRP3 inflammasome, most contended that it contributes to cancer pathophysiology." (PMID 36902299, 2023). "The NLRP3 inflammasome is more important than the other inflammasomes in cancer because it has a dual role in cancer progression and regression." (PMID 37715239, 2023). "Our findings coincide with these previous reports, highlighting the potential influence of LPS and ATP-induced NLRP3 inflammasome pathway, consequently impacting cancer cell behavior." (PMID 38026959, 2023). "P2RX7 activation in macrophages and DCs releases NLRP3 to increase IL-1β and IL-18 production and NLRP3 has pro- and anti-tumorigenic roles in cancers based on cytokine quantity." (PMID 36741002, 2023). "IL-1 β produced by NLRP3 promotes cancer cell proliferation and migration in NSCLC by repressing miR-101 via the COX2-HIF1 pathway." (PMID 37715239, 2023). "The present review aims to summarize the latest understanding of the role of the NLRP3 inflammasome and pyroptosis in gastrointestinal inflammation and cancer." (PMID 37891577, 2023). "Oxidative stress is generally accepted as a contributing mechanism in the pathogenesis of a wide range of disease conditions, including aging, chronic inflammation, diabetes, neurodegeneration, and cancer, where activation of NLRP3 is commonly observed." (PMID 36669831, 2023). "The NLRP3 inflammasome's role in various inflammation-related disorders, including cancer, made it an appealing prospective target for developing novel medications for treatment." (PMID 37715239, 2023). "Being an important player in the pathogenesis of cancer, the NLRP3 inflammasome comprises three crucial components: the NLRP3, the ASC (which consists of the CARD domain), and pro-caspase 1 (which bears effector functions)." (PMID 37893079, 2023). "Nevertheless, it is essential to acknowledge the context-dependent and sometimes contrasting effects of the NLRP3 inflammasome and its product, IL-1β, on tumorigenesis depending on various cancer cell types." (PMID 38026959, 2023). "To confirm that the inflammasome pathway is playing a role in cancer cachexia, we assessed the gene expression of Nlrp1 and Nlrp3, which were increased in T7 and T14." (PMID 37177862, 2023). "The inhibitor Oridonin, that targets the Cys 279 residue in the NACHT domain of NLRP3, and its analogs, have been tested in a variety of cancers, including CRC, PDA, GC and EC." (PMID 37891577, 2023). "NLRP3 is, therefore a two-edged sword—one that can be wielded by either the immune system or by the cancer." (PMID 37289257, 2023). "Here, we have described the possible mechanistic action of RRx-001 in inhibiting NLRP3 in cancer models." (PMID 36920652, 2023). "The NLRP3 inflammasome can also promote the onset of diverse cancer types, impacting important processes including proliferative, angiogenic, metastatic, and immunosuppressive activity." (PMID 37885032, 2023). "NLRP3 inflammasome should be explored further in different cancer subtypes, which is also the future direction of experimental research." (PMID 37300757, 2023). "The NLRP3 inflammasome appears to have different immunosuppressive effects depending on the cancer type, suggesting a connection with cancer type specificity." (PMID 37705746, 2023). "Studies on the relationship between NLRP3 and MPNs are still lacking but given the significant evidence of this protein in hematological diseases and cancer in general, there are excellent reasons to investigate the role of NLRP3 in the MPNs on several fronts." (PMID 36902299, 2023).
cancer (continued). "In its early phases, the immune system can suppress it via NLRP3 inflammasome activation and IL-18 secretion which in turn can trigger the NK cells to exert their cytotoxic potential against cancer cells." (PMID 36763290, 2023). "Although the role of NLRP3 inflammasome in cancer development is controversial, it is perceived as an attractive therapeutic target for cancer treatment." (PMID 37524704, 2023). "Altogether, this study showed a novel effect of ODZ for the regulation of NLRP3 inflammasome activation in vitro and in vivo, suggesting its potential for use in treating NLRP3-inflammasome-mediated immune disorders and cancer." (PMID 37047051, 2023). "Several NLRP3 inhibitors have been created, and some are currently undergoing clinical trials to treat cancer and inflammatory diseases." (PMID 36902299, 2023). "Nowadays, five compounds addressing specifically NLRP3 protein have been employed in cancer treatment, named: MCC950, so far the best characterized inhibitor in several contexts, CY-09, Oridonin, OLT1177 and Tranilast." (PMID 37891577, 2023). "Aberrant NLRP3 inflammasome activation has been recently recognized to play decisive role in the development and progression of several type of cancers, beside those belonging to the GI tract." (PMID 37891577, 2023). "Since the readout activity of NLRP3 is the release of mature inflammatory cytokines, we will focus in the next section on the role of IL-1β and IL-18 in cancer progression." (PMID 37298187, 2023). "NLRP3 inflammasome activation contributes to inflammation and cancer development and mediates pyroptosis in various diseases." (PMID 37547766, 2023). "The effect of NLRP3 activation on cancer progression in TNBC, MDA-MB-231 and HCC1806 cells, and MCF7 cells, expressing ER-α, PR, and low to moderate levels of HER2, was investigated." (PMID 36902278, 2023). "In the following sections, we highlight studies describing the role of the NLRP3 inflammasome-pyroptosis pathway in IBD and cancer development and progression, as well as NLRP3 protective capacities." (PMID 37891577, 2023). "The existing literature has not confirmed the direct relationship between FDX1 and NLRP3, but researchers suggested that ATP7A and NLRP3 are negatively correlated in pan-cancer." (PMID 37138870, 2023). "Most of these can assemble into the inflammasome complexes, including NLRP3, NLRP1, NLRP6, NLRC4, NAIP, AIM2, and pyrin, but NLRP3 is the undisputed protagonist of the inflammasome, involved in numerous cancers." (PMID 36902299, 2023). "Recently, NLRP3 inflammasome has caught the attention of many research groups due to its involvement in different types of cancer." (PMID 36763290, 2023). "Previous studies have indicated that the activation of NLRP3 inflammasome can contribute to cancer progression by releasing inflammatory cytokines such as IL-1β and IL-18." (PMID 38026959, 2023). "Regulation of NLRP3 inflammasome activity via PTMs is essential for cancer development and progression." (PMID 37047097, 2023). "Based on previous research, it is known that the activation of NLRP3 inflammasome can promote cancer progression by releasing inflammatory cytokines such as IL-1β." (PMID 38026959, 2023). "Previously, we demonstrated that the degree of NLRP3 inflammasome activation varies among cancer cell lines, resulting in different cancer cell growth patterns." (PMID 36902278, 2023). "Although cancer studies on NLRP3 and pyroptosis are still in an early stage, the rapid development of research technology, nanomaterials, natural and chemotherapeutic drugs, holds great potential in this field." (PMID 37891577, 2023). "The fine-tuning of the NLRP3 inflammasome in cancer cells using a variety of drugs such as inhibitors, antagonists, and monoclonal antibodies has been proposed as a potential cancer therapeutic method." (PMID 37715239, 2023).
cancer (continued). "In cancer research, NLRP3 inflammasome has been also widely explored, appearing to be relevant in such diverse tumors as glioblastoma, and colorectal or liver cancers." (PMID 37819510, 2023). "Because, NLRP-3 induces hypersecretion of several cytokines involved in cardiovascular diseases and cancer, we analyzed systemic and myocardial cytokines and growth factors levels." (PMID 37684243, 2023). "SNV frequency analysis indicated that NLRP3 had the highest SNV percentage (65%) in LUAD, and the SNV classification of missense mutation was the predominant type in pan-cancer." (PMID 36890219, 2023). "For example, quercetin modulated the MAPK, NF-κB, and NLRP3 to alleviate the inflammatory pain, neuropathic pain, and cancer pain." (PMID 38047157, 2023). "What's more, the NLRP3 inflammasome blockade during cancer treatment plays an antagonistic role in anti-PD-L1 therapy due to an imbalance in T cell proportion." (PMID 37705746, 2023). "It has been reported that inhibiting the activation of NLRP3 inflammasomes can suppress cancer cell inflammation and tumorigenesis." (PMID 37715239, 2023). "The evidences indicate that autophagy, NLRP3 inflammasome and apoptosis are interrelated and play an important role in cancer." (PMID 37153780, 2023). "Many studies have demonstrated that NLRP3 inflammasome not only participates in tumorigenesis, but also plays a protective role in some cancers." (PMID 37153780, 2023). "NLRP3 can be activated through cross-talk between TAMs and cancer cells leading to promoted migration of cancer cells in IL-1β dependent manner." (PMID 36932407, 2023). "The clinical importance of the NLRP3 inflammasome in several cancers underscores its therapeutic potential as a molecular target." (PMID 37715239, 2023). "Of note, the NLRP3 inflammasome inhibition during cancer treatment plays a synergistic in anti-PD-1 treatment." (PMID 37705746, 2023). "Recently, it has been reported that the NLRP3 inflammasome is closely related to the development of several types of cancer." (PMID 37524704, 2023). "When activated, the NLRP3 inflammasome stimulates the release of pro-inflammatory cytokines IL-1β and IL-18, which promote the progression of cancer." (PMID 37345134, 2023). "Owing to the extensive participation of the NLRP3 pathway in several inflammatory diseases and cancers, a variety of chemical NLRP3 inhibitors has been proposed, with some of them tested in a clinical setting." (PMID 37834268, 2023). "It has been established that the NLRP3 inflammasome is involved in many cancer-immune relationships, with both antitumorigenic and pro-tumorigenic roles." (PMID 37794178, 2023). "Specifically, we have detailed the role of the NLRP3 inflammasome pathway in promoting cancer cell growth, invasion, and metastasis." (PMID 38026959, 2023). "Mechanistically, it has been shown that estrogens upregulate NLRP3 expression via estrogen receptor β (ERβ), which foster cancer cells proliferation; accordingly, NLRP3 knockdown inhibited cancer growth." (PMID 37891577, 2023). "The aggressive behavior of cancer is due to the miR-21 activity, which inhibits the NLRP3 assembly by regulating NLRP3 phosphorylation and lysine 63-ubiquitination and alters the normal functions of the innate immune system." (PMID 36834660, 2023). "Nucleotide-binding domain (NOD)-like receptor protein 3 (NLRP3) is the most widely investigated inflammasome member whose overactivation can be a driver of several carcinomas." (PMID 36902299, 2023). "RRx-001 was developed as an anti-cancer molecule that can covalently interact with NLRP3 and block the NLRP3–NEK7 interaction." (PMID 36555757, 2022). "A study found that a deletion of NLRP3 suppresses cancer development and metastasis of HCC cells in vitro and in vivo." (PMID 36389791, 2022). "The role of NLRP3 in cancers is dual and it has hostile and amicable effects toward different cancers." (PMID 35877745, 2022).
cancer (continued). "The concomitant effects of IL-18, IL-1β and NLRP3 elevation were ignored in studies claiming that GSDMD mediates pyroptosis in cancer cells." (PMID 36091247, 2022). "It has been reported that the inflammation and tumorigenesis of cancer cells can be suppressed by inhibiting the activation of NLRP3 inflammasomes." (PMID 35890097, 2022). "The P2X7R/NLRP3 complex lacks detailed studies in OC, and the pro- and anti-inflammatory and even pro- and anti-cancer responses it mediates are incompletely understood as well." (PMID 35964092, 2022). "GL/GA has been shown to play a key role in metabolic diseases, cancers, and respiratory diseases through the regulation of inflammatory signaling pathways such as NLRP3 and NF-κB." (PMID 35967372, 2022). "We have also demonstrated that the effect of NLRP3 activation on cancer cell survival depends upon inflammasome mediated cytokine release." (PMID 36012769, 2022). "While the direct effects of NLRP3 are responsible for the secretion of IL-1β and IL-18, the other effects of NLRP3 can promote cancer cells to the EMT process and metastasis." (PMID 35890097, 2022). "Evidence states that polymorphisms in the NLRP3 inflammasome gene are linked with CVD and cancer development." (PMID 36466820, 2022). "In contrast, the effect of Az on LPS primed NLRP3 and the inflammatory cytokines production appears to depend on the cancer cell origin." (PMID 36012769, 2022). "Several genes and gene products were identified as targets of miR-223, including NLRP3, IL18, IL1β, DNA methyltransferase 1, and checkpoint kinase-1, signifying its potential use as a cancer-specific diagnostic biomarker and therapy." (PMID 35205115, 2022). "Although lactamides and macrolides are frequently used for treating a bacterial infection in cancer patients, our understanding of these antibiotics’ effects on NLRP3 activation remains limited." (PMID 36012769, 2022). "On the one hand, inflammatory factors released accompanying cancer cell pyroptosis form a chronic inflammatory microenvironment, including NLRP3, IL-18 and IL-1β." (PMID 36091247, 2022). "Overall, these data demonstrate the value of NLRP3 as a PRG that is independently associated with HNSCC patient survival and cancer development." (PMID 35123464, 2022). "Within the family of inflammasome proteins, NLRP3 is primarily shown to be involved in cancer development and progression." (PMID 36012769, 2022). "This was urged by the caspase-11/NLRP3 inflammasome, which pressed on through immune regulation and decreased cancer cell proliferation in vitro and xenograft tumors in mice." (PMID 36119049, 2022). "Increasing evidence highlights the pivotal role of Ca-EVs on NLRP3 activation in different types of cancers." (PMID 35530309, 2022). "A third group of cancers comprised of BLCA, BRCA, UCEC, LIHC, STAD, PRAD and THCA showed a similar expression pattern with first group of cancers except for the contrast behavior of NLRP3, NLRC4, PRF1, CASP1, CASP4, and GZMA (downregulated in this group)." (PMID 36605187, 2022). "The upregulation of NLRP3 can regulate the inflammatory responses in cancer cells and then enhance cancer progression." (PMID 35890097, 2022). "GSDMC, GSDMD, GSDME, ZBP1, AIM2, DHX9 and NLRP3 demonstrated significant amplification across cancers." (PMID 36605187, 2022). "This study found a high degree of consistency between Fn infection, high NLRP3 expression and MDSCs enrichment in the cancer tissues from 258 ESCC patients treated with conventional TP chemotherapy." (PMID 35435776, 2022). "The relationship between NLRP3 inflammasome and malignant tumors is complex and has some tissue or cell specificity." (PMID 35513871, 2022). "Abnormal activation of NLRP3 inflammasomes has recently been found in various cancer types; however, the role of NLRP3 inflammasomes in 5-FU chemoresistance of CRC cells has not been clearly elucidated." (PMID 35890097, 2022).